STARD3 (StAR related lipid transfer domain containing 3)
Description:
Sterol-binding protein that mediates cholesterol transport from the endoplasmic reticulum to endosomes. The sterol transport mechanism is triggered by phosphorylation of FFAT motif that leads to membrane tethering between the endoplasmic reticulum and late endosomes via interaction with VAPA and VAPB. Acts as a lipid transfer protein that redirects sterol to the endosome at the expense of the cell membrane and favors membrane formation inside endosomes. May also mediate cholesterol transport between other membranes, such as mitochondria membrane or cell membrane. However, such results need additional experimental evidences; probably mainly mediates cholesterol transport from the endoplasmic reticulum to endosomes. Does not activate transcriptional cholesterol sensing. Able to bind other lipids, such as lutein, a xanthophyll carotenoids that form the macular pigment of the retina.
Synonyms: CAB1; MLN64; es64
Tractability: Small molecule: a structure with a bound ligand is known; it has a binding pocket of medium quality. Antibody: UniProt predicts a signal peptide or a membrane-spanning region. PROTAC: ubiquitination databases record sites on it; its protein half-life has been measured.
Gene: Protein-coding gene on chromosome 17 (39,637,090 to 39,664,201, forward strand). Ensembl gene ENSG00000131748.
Subcellular location: Late endosome membrane
Subcellular location (Human Protein Atlas): Nucleoplasm; Vesicles; Endoplasmic reticulum
Pathways (Reactome):
Metabolism: Pregnenolone biosynthesis
Gene Ontology:
Molecular function: cholesterol binding; cholesterol transfer activity; protein binding; protein homodimerization activity; lipid binding
Biological process: cholesterol transport; cholesterol metabolic process; lipid metabolic process; mitochondrial transport; steroid metabolic process
Cellular component: endoplasmic reticulum membrane; endoplasmic reticulum-endosome membrane contact site; endosome; late endosome membrane; lysosomal membrane; organelle membrane contact site; cytoplasm; cytosol; late endosome; mitochondrion
Genetic constraint (gnomAD): Loss-of-function variants: 41 observed, 65.52 expected, observed/expected ratio (o/e) 0.63, 90% interval 0.49 to 0.81. The upper end of that interval is the gene's LOEUF score, 0.81, which puts it in group 3 of 6, group 1 being the genes least tolerant of losing a copy. Missense variants: 543 observed, 599.41 expected, observed/expected ratio (o/e) 0.91, 90% interval 0.84 to 0.97. Synonymous variants: 229 observed, 248.04 expected, observed/expected ratio (o/e) 0.92, 90% interval 0.83 to 1.03.
Homologues: Orthologues: macaque STARD3 (98% identical), dog STARD3 (96% identical), mouse Stard3 (94% identical), rat Stard3 (93% identical), rabbit STARD3 (91% identical), guinea pig STARD3 (91% identical), chimpanzee STARD3 (88% identical), pig STARD3 (83% identical), zebrafish stard3 (69% identical), Drosophila melanogaster Start1 (33% identical), Caenorhabditis elegans tag-340 (28% identical). Paralogues in human: STARD3NL (31% identical), STAR (23% identical), STARD5 (12% identical), STARD4 (12% identical), STARD6 (11% identical).
Diseases named in the same sentence as STARD3 in open-access papers:
STARD3 is named in the same sentence as 47 diseases in open-access papers, as found by Europe PMC text mining. Sharing a sentence is not in itself a finding about the gene and the disease. The quoted sentences say what the papers report.
breast carcinoma (32 papers, 2006 to 2025). "Several studies have found an association of STARD3 with different cancer types, including lung, pancreatic, gastric ovarian and especially breast cancers for which high STARD3 expression is associated with recurrence, metastasis and poor prognosis." (PMID 40506516, 2025). "HER2-amplified breast cancers have a particular tendency toward STARD3 expression, and STARD3 co-expression is implicated toward pCR in HER2-amplified breast cancers." (PMID 39063972, 2024). "This article studied on a group of 112 patients with HER2-positive breast cancer, the presence of a protein called STARD3, which has a strong biological and genetic association with HER2." (PMID 36672312, 2023). "Considering all breast cancer subtypes, STARD3 expression is associated with a poorer prognostic, like HER2 expression." (PMID 36672312, 2023). "We studied the association of STARD3 expression and breast cancer-specific survival and compared it to other relevant patient and tumor characteristics in this HER2-positive series." (PMID 36672312, 2023). "STARD3 expression is associated with HER2+ breast cancers (BCs); thus, STARD3 has the potential to be a diagnostic and predictive marker of HER2+ BC." (PMID 35386193, 2022). "The first STARD3 inhibitor to be analyzed, a compound named VS1, was shown to bind to STARD3 and steer it for degradation, causing antiproliferative activity in colon and breast cancer cell lines." (PMID 34281263, 2021). "The possible role played by STARD3 as a diagnostic and prognostic biomarker was investigated in breast cancer (BC)." (PMID 34268252, 2021). "Different studies have reported the association of STARD3 expression with several cancer types, and in breast cancer patients, a high level of STARD3 is associated with metastasis, local recurrence, and shorter overall survival." (PMID 34572920, 2021). "In human epidermal growth factor receptor 2 (HER2/neu, c-erbB2) positive breast cancer cells, STARD3 is associated with a poor prognosis, and lower levels of STARD3 increase cell death while reducing cell proliferation." (PMID 30717356, 2019). "It has previously been shown that overexpression of STARD3 is associated with increased cholesterol biosynthesis in HER2+ breast cancer subtype." (PMID 31060224, 2019). "High StARD3 protein levels with a strong association with HER2 amplification was reported for approximately 10% of breast cancers in two Finnish nationwide patient cohorts." (PMID 29867922, 2018). "The overexpression of the STARD3 gene, which encodes a cholesterol-binding membrane protein, could decrease cell adhesiveness, promote breast cancer metastases, and be associated with a poor prognosis for breast cancer patients." (PMID 36085159, 2022). "StARD3 was first found in the metastatic axillary lymph nodes of human breast cancer cells; it has a START domain and belongs to the same subfamily as StAR in the START domain protein family." (PMID 41007402, 2025). "Of interest, this reasoning is consistent with a previous report on STARD3 protein expression in a Finnish breast cancer patient cohort." (PMID 36672312, 2023). "Collectively, STARD3 expression quantified with a binary score considering the localization of the protein has a predictive value on NST-treated HER2+ breast cancers." (PMID 36672312, 2023). "The objective of this study was to investigate the prognostic and predictive value of STARD3 protein expression on NST pathological responses in HER2-positive breast cancer." (PMID 36672312, 2023). "Next, we assessed the prognostic value of STARD3 gene expression on all breast cancers using a public online database with KMplot." (PMID 36672312, 2023). "Altogether, these data confirmed the strong correlation between STARD3 and HER2 DNA amplification and RNA expression in breast cancer and prompted us to examine STARD3 protein expression in a clinical series by IHC using a specific anti-STARD3 antibody." (PMID 36672312, 2023).
breast carcinoma (continued). "Given the in vitro dependence of HER2-positive cells to STARD3, and the findings of this study, STARD3 can be a possible therapeutic target in HER2-positive breast cancer." (PMID 36672312, 2023). "In this study, we assessed the predictive value of STARD3 protein expression on a cohort of primary breast cancer specimens from the HER2-positive subtype that were all treated by neoadjuvant therapy." (PMID 36672312, 2023). "The objective of this study was to investigate the predictive value of STARD3 protein expression on NST pathological response in HER2-positive breast cancer." (PMID 36672312, 2023). "Other therapeutic approaches included StARD3 depletion in combination with lapatinib, which prominently reduced cell viability and proliferation, and increased apoptosis in breast cancer cells." (PMID 35806209, 2022). "Elevated StARD3 levels also correlate with metastasis, tumour recurrence and shorter survival in breast cancer and possibly colorectal, prostate, gastric and pancreatic cancer progression." (PMID 35022465, 2022). "In contrast, StARD3 depletion decreased HER2-positive breast cancer cell proliferation and cell cycle progression." (PMID 35806209, 2022). "Numerous genes located in 17q12 region have been implicated in diverse cancers, such as ERBB2 for gastric cancer 38 and breast cancer 39, CDK12 for prostate cancer 40, and STARD3 for breast cancer." (PMID 36147475, 2022). "Like breast cancer, StARD3 was co-amplified with HER2 in gastric cancer and correlated with poor prognosis." (PMID 35806209, 2022). "The consensus “HER2 amplicon” in breast cancers located at the 17q12–21 chromosomal region contains (besides ERBB2) at least five other genes (STARD3, TCAP, PNMT, PGAP3, and MIEN1)." (PMID 36139701, 2022). "It has been shown that inducing STARD3 overexpression elevates HER2 positive breast cancer proliferation, and ablating this expression returns an opposite effect." (PMID 34281263, 2021). "StAR related lipid transfer domain containing 3 (STARD3) gene has been reported to be co-amplified with human epidermal growth factor receptor 2 (HER2) in breast carcinoma." (PMID 34268252, 2021). "Currently, it is unclear how STARD3 enhances tumorigenesis of HER2-positive breast cancer and how the two proteins cooperate." (PMID 32039198, 2019). "When STARD3 is amplified or overexpressed in HER2-positive breast cancer, the endosomal membranes are wrapped by the ER, leading to rigid and static ER-LE MCSs, thus losing their transient and dynamic features." (PMID 32039198, 2019). "Higher levels of STARD3 also decrease the adhesiveness of breast cancer cells, which promotes metastases." (PMID 30717356, 2019). "Studies have reported that STARD3 expression plays a role in focal adhesion kinase, and correlates with adhesive capacity and prognosis in breast cancer patients." (PMID 30662464, 2018). "Moreover, they found a significant association between STARD3 mRNA levels and worse overall survival in HER2-positive breast cancers." (PMID 36672312, 2023). "In this study, we investigated STARD3 expression on a cohort of HER2-positive breast cancers." (PMID 36672312, 2023). "Several studies reported a poor prognostic value for STARD3 expression in breast cancers." (PMID 36672312, 2023). "This hypothesis is supported by the experimental data obtained by Vassilev and colleagues, who showed that STARD3 overexpression enhances oncogenic signals in breast cancer cell lines." (PMID 34572920, 2021). "Our findings suggest that STARD3 may have strong diagnostic and prognostic value for HER2+ breast carcinoma." (PMID 34268252, 2021). "STARD3 gene is located in the minimal amplicon of HER2-positive breast cancers." (PMID 32039198, 2019). "Indeed, it was shown that STARD3 overexpression increases the proliferation rates of HER2-positive breast cancer cells, while its knockdown has an opposite effect." (PMID 32039198, 2019).
breast carcinoma (continued). "Although the direction of cholesterol transfer mediated by StARD3 and its potential contribution to intratumoral steroid production in estrogen-responsive tumors is still unclear, elevated StARD3 expression may promote breast cancer cell migration and invasion." (PMID 35806209, 2022). "STARD3 overexpression results in increased cholesterol biosynthesis and Src kinase activity in breast cancer cells and suggest that elevated StARD3 expression may contribute to breast cancer aggressiveness by increasing membrane cholesterol and enhancing oncogenic signaling." (PMID 27506935, 2016). "StAR-related lipid transfer domain-3 (STARD3) is co-amplified and co-expressed with HER2 in breast cancer." (PMID 39063972, 2024). "In our laboratory, we have identified a gene named StAR-related lipid transfer domain-3 (STARD3) co-amplified and co-expressed with HER2 in breast cancer." (PMID 36672312, 2023). "We extracted DNA copy number and RNA expression data for HER2, GRB7, STARD3, and TOPA2 genes in 51 breast cancer cell lines." (PMID 36672312, 2023). "Specifically, Sahlberg and colleagues proved that silencing either STARD3, GRB7, PSMD3, PERLD1, PPP1R1B, THRA, or GSDMA partially sensitized specific breast cancer cell lines to anti-HER2 agents." (PMID 36139701, 2022). "Elevated StARD3 levels correlated with poor overall survival, disease metastasis-free survival and relapse-free survival in HER2-positive breast cancer and a lower response to trastuzumab therapy." (PMID 35806209, 2022). "Cluster 2 (dark-blue) consisted of genes that are up-regulated in HER2+ breast cancer, including ERBB2, GRB7, STARD3 and PSMD3 that are located in the HER2 amplicon." (PMID 23945349, 2013). "Previous studies have shown that STARD3 co-amplified and co-expressed with HER2 in breast cancer." (PMID 37966613, 2023). "Indeed, coamplification of STARD3 and HER2/receptor tyrosine-protein kinase erbB-2 (ERBB2) genes contributes to the proliferation and metastasis of breast cancer cells by increasing membrane cholesterol and thereby improving oncogenic signaling." (PMID 34572920, 2021). "However, the minimum region of recurrent amplification within the 17q12 amplicon includes just the STARD3, ERBB2 and GRB7 genes in human breast cancer." (PMID 19424485, 2008). "For example, the StAR-related lipid transfer protein 3 (STARD3) gene overexpression is evident in a variety of breast carcinomas and especially in connection to HER2 amplification, exhibiting decreased adhesiveness of breast cancer cells as well as increased metastasis, and poor patient prognosis." (PMID 39243069, 2024). "Hence, StARD3 is often (~25%) co-amplified with HER2 and highly expressed in breast carcinomas." (PMID 35806209, 2022). "For example, STARD3, PNMT, CAB2, C17ORF37 and GRB7 show a significant correlation between amplification status and expression level, and STARD3, PNMT, CAB2, GRB7 and ZNFN1A3 could all be biologically relevant to breast cancer." (PMID 17117180, 2006). "Thus, it is perhaps not surprising that STARD3 is classically co-amplified and co-expressed with HER2 in approximately 10–25% of breast cancers." (PMID 34281263, 2021).
gastric cancer (14 papers, 2010 to 2022). A primary or metastatic malignant neoplasm involving the stomach. "While little information is available regarding the possible contribution of STARD3 to the pathophysiology of lung cancer, it has been associated with breast, colon, and gastric cancers." (PMID 34281263, 2021). "Interestingly, the fusion of StARD3 with the gene encoding protein phosphatase 1 regulatory inhibitor subunit 1B in >20% of primary human gastric cancers might increase cell proliferation through activation of the PI3K/Akt pathway." (PMID 35806209, 2022). "In gastric cancer, StARD3 upregulation was proposed to stimulate cholesterol transfer to mitochondria to activate steroidogenesis and improve mitochondrial homeostasis, accelerating cancer cell survival." (PMID 35806209, 2022). "Recently, STARD3 has been determined to be involved in the development of several types of cancer, e.g., colorectal, prostate, and gastric cancers." (PMID 34268252, 2021). "Differently from others START proteins, STARD3 is mapped in 17q12-21, a chromosomal region frequently amplified in many cancers including breast, colorectal, and gastric cancers." (PMID 34572920, 2021). "STARD3 can promote the occurrence and development of gastric cancer via activating the PI3 K / AKT signaling pathway." (PMID 33090721, 2020). "rs1877031 genotype TC has been reported to promote histogenesis in gastric cancer, and STARD3 haplotype CCCT (rs9972882, rs881844, rs11869286, and rs1877031) conferred a protective effect on susceptibility to gastric cancer." (PMID 30662464, 2018). "For example; in gastric cancers the frequently amplified 17q12-q21 region contains genes such as ERBB2, GRB7, JUP, PERLD1, PNMT, PPP1R1B, STARD3, and TOP2A." (PMID 20187983, 2010).
breast tumor (4 papers, 2019 to 2023). "Whereas StAR was found to be distinctly expressed in human and/or mouse hormone-sensitive breast tumor cells and tissues, an involvement of STARD3, a late endosomal membrane protein with ~37% C-terminal homology to StAR, cannot be excluded." (PMID 36614200, 2023). "In our previous studies, using cell lines and breast tumors, we showed that STARD3 gene amplification and overexpression paralleled that of HER2." (PMID 36672312, 2023). "The results showed that nearly 10% of breast tumors showed high STARD3 expression when anti-STARD3 affinity-purified antibody was used." (PMID 34268252, 2021). "STARD3 was originally named metastatic lymph node clone 64 protein (MLN64) since it was discovered in a screen designed to identify human genes that were amplified or overexpressed in aggressive breast tumor." (PMID 32039198, 2019). "In addition, STARD3 was overexpressed in breast tumor tissues compared with adjacent normal breast tissues." (PMID 34268252, 2021).
prostate carcinoma (4 papers, 2017 to 2023). A carcinoma that arises from epithelial cells of the prostate gland. "In this regard, unbalanced expression of STARD3 and CYP17 is associated with a poor prognosis in prostate cancer patients." (PMID 34572920, 2021). "In prostate cancer, it was found a linear correlation between the expression of STARD3 and CYP17, an enzyme involved in the steroid biosynthesis pathway." (PMID 34572920, 2021). "The amplification/overexpression of STARD3 in cancer potentially could stimulate an independent steroidogenesis helping the promotion of hormone-driven cancers, such as breast and prostate cancers." (PMID 34572920, 2021). "Furthermore, STARD3 could also be implicated in other HER2-positive cancers, such as ovarian, gastric, pulmonary, vesical, and prostatic cancers." (PMID 36672312, 2023). "In different types of cancers, such as steroid hormone-driven cancers (breast and prostate cancers), the amplification/overexpression of STARD3 could promote intra-neoplastic autonomous steroidogenesis and contribute primarily to the development of the malignancy." (PMID 34572920, 2021). "In addition, the authors thought that STARD3 and CYP17 expression in prostate cancer could lead to steroidogenesis through continuous cholesterol transfer into the mitochondria, increasing androgen biosynthesis via the catalytic activity of cytochrome CYP17." (PMID 34572920, 2021).
asthma (3 papers, 2013 to 2024). "For example, SNPs at STARD3/PGAP3 are strongly associated with the high atopic dermatitis subgroup suggesting that STARD3/PGAP3 may act on the allergic component of asthma." (PMID 29855310, 2018). "Some of the SNPs are in or close to the genes PGAP3 and STARD3 on chromosome 17, and interestingly, rs2941504 has been reported in a recent independent study to be associated with asthma, although it does not meet the criteria for inclusion in the GWAS catalog." (PMID 23755072, 2013).
hypospadias (3 papers, 2020). Hypospadias is the displacement of the urethral meatus on the ventrum of the penis. "Polymorphisms, mutations, and epigenetic changes in the AR, CYR61, HSD17B3, HSD3B1, MAMLD1, SRD5A2, and STARD3 have been associated to hypospadias risk in severe types of hypospadias that have not been found in mild hypospadias." (PMID 33425810, 2020).
colon cancer (2 papers, 2021 to 2022). "Recently, the in silico development of the StARD3 inhibitor VS1, which has moderate potency but specifically induced StARD3 degradation, reduced cell viability of breast and colon cancer cell lines." (PMID 35806209, 2022). "Recently, a STARD3 inhibitor was developed and tested in several BC and colon cancer cell lines but not in HER2+ cells." (PMID 34268252, 2021).